TLR4 (toll like receptor 4)
Diseases named in the same sentence as TLR4 in open-access papers (continued):
Sharing a sentence is not in itself a finding about the gene and the disease.
heart failure (continued). "Numerous studies have demonstrated that TLR4 activation-mediated leucocyte infiltration in myocardium leads to cytokine secretion, oxidative stress, and protease release, which play a pivotal role in myocardial infarction, ischemia-reperfusion injury, myocarditis, and heart failure." (PMID 30046376, 2018). "In addition, the expression of TLR4 in cardiac tissue may determine the efficacy of βAR agonists as (such as ISOP) agents to induce heart failure." (PMID 28824368, 2017). "Activation of TLR4, caspase-1, IL-1β, and mast cells are also known to increase myocarditis and promote remodeling, fibrosis, and DCM in CVB3 myocarditis in male mice suggesting that BPA exposure could increase the risk of progression from myocarditis to DCM and heart failure in women." (PMID 31551929, 2019). "In the present study, ICV injection of TLR4-SiRNA reduced LV dimension and LVEDP, and improved LVEF and cardiac output with sympathoinhibition in MI-induced heart failure." (PMID 23874864, 2013). "The link between inflammatory TLR4 signaling and regulation of ion channels in LV structural and electrical remodeling further support importance of accessory molecule MD1 as potential therapeutic strategy in heart failure." (PMID 35237675, 2022). "In fact, TLR4 is upregulated in the infarcted and noninfarcted myocardium following ischaemia/reperfusion injury and in heart failure." (PMID 33505220, 2021). "Moreover, inhibition of endogenous expression of TLR4 and NADPH oxidase 4 that were upregulated in rat cardiac tissue after heart failure, showed heart failure relief by suppressing ferroptosis in cardiac cells." (PMID 34312370, 2021). "LV percent fractional shortening (%FS) was not different between in MI-induced heart failure treated with TLR4-SiRNA and that treated with hGAPDH-SiRNA for 2 weeks." (PMID 23874864, 2013). "The novel finding of the present study is that partially silencing brain TLR4 by ICV injection of TLR4-SiRNA for 2 weeks inhibited enhanced central sympathetic outflow and in part prevented LV remodeling in rats with MI-induced heart failure." (PMID 23874864, 2013). "Although we did not investigate direct ligand for TLR4 in the previous studies, we considered that there would be a connection between brain angiotensin II type 1 receptor and brain TLR4 in mice with heart failure." (PMID 23874864, 2013). "Because TLR4 signal is involved in pro-inflammatory cytokines release and contribute to CAD and heart failure, let-7i may be a participator in CAD via TLR4." (PMID 24284400, 2013). "Elevated TLR4 expression on mast cells and macrophages in the spleen and heart of CVB3 infected males not only increases acute myocarditis but induces expression of the profibrotic cytokine IL-1β resulting in cardiac dilatation and heart failure later." (PMID 21338512, 2011). "After knocking down TLR4, autophagy and ferroptosis could be alleviated through the TLR4 and NADPH oxidase 4 (NOX4) pathway, which provides a potential treatment strategy for heart failure." (PMID 34262953, 2021). "It appears that TLR4 is particularly important for continuous monocyte activation in heart dysfunction, and that TLR4 overexpression is accompanied by secretion of proinflammatory cytokines such as CRP and TNF-α, as well as a known biomarker of cardiac failure—pro BNP." (PMID 26030867, 2015). "The present study suggests that brain TLR4-mediated inflammatory cascade, probably not in plasma and heart, might in part exacerbate LV remodeling with sympathoexcitation in MI-induced heart failure." (PMID 23874864, 2013). "Considering these backgrounds, in the present study, we examined whether silencing brain TLR4 by ICV injection of TLR4-SiRNA could prevent LV remodeling with sympathoinhibition in MI-induced heart failure or not." (PMID 23874864, 2013). "However, the expressions of IL-1β and IL-6 were not different between in MI-induced heart failure treated with TLR4-SiRNA and that treated with hGAPDH-SiRNA for 2 weeks." (PMID 23874864, 2013).
heart failure (continued). "Although we did not check the effect of the ICV injection of TLR4-SiRNA on plasma and/or heart cytokines, we consider that brain TLR4-mediated inflammatory cascade might be involved in LV remodeling with sympathoexcitation in MI-induced heart failure." (PMID 23874864, 2013). "However, it has not been clarified whether direct inhibition of brain TLR4 could prevent LV remodeling with sympathoinhibition in MI-induced heart failure or not, because the no suitable direct inhibitor of TLR4 has been available." (PMID 23874864, 2013).
prostate carcinoma (80 papers, 2010 to 2026). A carcinoma that arises from epithelial cells of the prostate gland. "Several studies have reported associations between single nucleotide polymorphisms (SNPs) in TLR4 and prostate cancer risk." (PMID 41601666, 2026). "In prostate cancer, cancer-associated fibroblasts (CAFs) mediate TLR-4-dependent inhibition of T-cell proliferation, contributing to immunosuppression." (PMID 40404908, 2025). "In this study, the overexpression of SLAMF8 in prostate cancer cells caused an increase in TLR4 expression, triggered the NF-κB signaling pathway, and led to higher IL-6 secretion, potentially contributing to an immunosuppressive tumor microenvironment." (PMID 41162970, 2025). "Specifically, in prostate cancer, the expression of TLR4 and its association with chronic inflammation, such as that mediated by interleukin-6 (IL-6)." (PMID 41162970, 2025). "Cellular experiments show that ligustilide significantly inhibits prostate cancer and prostate cancer-associated fibroblasts and induces apoptosis of prostate cancer-associated fibroblasts through the TLR4 pathway." (PMID 39210410, 2024). "With regard to rs11536889, a locus located in the exon 3 of TLR4, its G/C variation was found to be relevant to prostate cancer risk among populations within Sweden and South Korea (OR=1.26, 95% CI: 1.01-1.57)." (PMID 30944713, 2019). "Other studies showed that the detection TLR4 Asp299Gly polymorphism had a 4-fold higher risk for development of prostate cancer, among a North Indian population." (PMID 29883450, 2018). "TLR4 expression and its attendant chronic inflammation (e.g., IL-6) are associated with faster progression and poorer treatment outcomes in prostate cancer." (PMID 29928275, 2018). "Another large study including 1383 prostate cancer patients and 780 age-matched controls in Sweden revealed that the frequencies of the variant genotypes of TLR4 rs11536889 were significantly higher in patients (24.1%) than in controls (19.7%)." (PMID 28002812, 2017). "A synthetic meta-analysis based on data from 22 studies also confirmed the association of TLR4 SNP Asp299Gly with increased gastrointestinal cancer risk but with decreased prostate cancer risk." (PMID 26771524, 2016). "A large study that included prostate cancer patients and age-matched controls from Sweden revealed an association between TLR4 rs11536889 and prostate cancer." (PMID 24950711, 2014). "Single nucleotide polymorphisms (SNPs) in TLR4 were reported to be associated with prostate cancer risk in several studies." (PMID 25101092, 2014). "Characteristics of the study populations that evaluated the relationship between TLR4 polymorphisms and risk of prostate cancer." (PMID 25360682, 2014). "For example, two studies have shown a statistically significant association to exist between TLR4 rs11536889 and the risk of prostate cancer." (PMID 23565226, 2013). "Sequence variants of TLR4 are associated with prostate cancer risk and sequence variants of TLR4 and TLR10 are associated with nasopharyngeal cancer risk." (PMID 22985132, 2012). "Recently, several studies showed that variants in TLR4 were related with the risk of prostate cancer in Eastern Asian population or Western population." (PMID 21559380, 2011). "It has also been shown that Toll-like receptor 4 (TLR4) is expressed in the prostate gland and its expression is closely associated with the severity of prostate cancer." (PMID 21267413, 2011). "Additionally, peroxiredoxin 1 (Prx1) has been implicated as a TLR4 agonist in prostate cancer progression." (PMID 41601666, 2026). "However, the results from a meta-analysis suggest that the TLR4 Asp299Gly polymorphism had a protective effect in prostate cancer; whereas, both TLR4 Asp299Gly and Thr399Ile polymorphisms were associated with an elevated gastrointestinal cancer risk." (PMID 29883450, 2018).
prostate carcinoma (continued). "TLR4 activation in prostate cancer cells promotes tumor progression: LPS stimulation in DU145 cells triggers NF-κB–dependent production of IL-6 and IL-1β, while in PC3 cells it enhances VEGF and TGF-β1 expression." (PMID 41601666, 2026). "Genes linked to prostate cancer susceptibility, including RNASEL, MSR1 and MIC1, found in areas associated with familial prostate cancer, as well as TLR4, MIC1, PON1, BRCA2, CHEK2 and OGG, have been identified as contributors to prostate cancer development." (PMID 38971935, 2025). "On the other hand, LPS can also activate TLR4 and induce the LPS/TLR4 signaling pathway to promote prostate cancer development and progression." (PMID 40520902, 2025). "In support, it has recently been shown that DVL3 increases the proliferation and migration of prostate cancer cells via the Toll-like receptor 4 (TLR4) pathway." (PMID 39596188, 2024). "In prostate cancer, in vitro activation of TLR4 by LPS promoted proliferation and survival of prostate epithelial PC3 cancer cells through the VEGF and TGF-β dependent pathways, while TLR4 silencing via small interfering RNA showed the opposite effect." (PMID 38201300, 2024). "BPH tissues and prostate cancer cells express toll-like receptor 4 (TLR4) and are characterized by increased immune-mediated inflammatory processes and secretion of cytokines, such as IL-1β, IL-6, IL-8, TNF-α, and COX-2." (PMID 36771389, 2023). "We found that ligustilide can inhibit the secretion of VEGFA from prostate cancer-related fibroblasts (CAFs), and this signaling pathway is related to Toll-like receptor 4 (TLR4)-ERK/JNK/p38." (PMID 35626012, 2022). "Gram-negative bacterial cell wall component, LPS, is recognized by TLR4, and activation of TLR4 promotes prostate cancer development and induces nitric oxide and IL-6 production in CRC." (PMID 36003378, 2022). "In that study, TAK-242-attenuated prostate cancer cell migration was shown to be dependent on ERG (transcription factor) activated TLR4 gene expression." (PMID 36232715, 2022). "While LNCaP-1 and LNCaP2 (2 human prostate cancer cell lines) and H1437-1 and H1437-2 (2 human lung adenocarcinoma cell lines) demonstrated an open TLR4 gene region close to chr6:118050000." (PMID 35801728, 2022). "Studies have found that silencing TLR4 expression can inhibit invasion in prostate cancer, suggesting that TLR4 plays an important role in tumor invasion." (PMID 33576897, 2021). "It has been previously reported that ERG can drive TLR4 expression in prostate cells and that TLR4 signaling can contribute to an invasive phenotype in prostate cancer cells." (PMID 33554122, 2021). "It has been reported that nobiletin inhibits the growth of prostate cancer cells by suppressing TLR4/TRIF/IRF3, TLR9/IRF7 and AKT signaling pathways." (PMID 34548474, 2021). "In prostate cancer specifically, TLR4 knockdown can reduce survival and invasion, and this has been attributed to TLR4’s canonical downstream effectors such as NF-kB." (PMID 33554122, 2021). "Another study proved that TLR4 and COX-2 are highly expressed in prostate cancer cells and showed that the inhibition of TLR4 and COX-2 obviously suppressed cell proliferation, migration, and invasion." (PMID 33576897, 2021). "Together these data indicate a mechanistic basis for inhibition of TLR4 signaling as a treatment for ERG-positive prostate cancer." (PMID 33554122, 2021). "A previous report indicated that knockdown of TLR4 in PC3 prostate cancer cells can reduce invasion and proliferation." (PMID 33554122, 2021). "Future work will be important to examine how TLR4 inhibition affects ERG-positive prostate cancer in animals with an intact immune system and possible synergies with other treatments." (PMID 33554122, 2021).
prostate carcinoma (continued). "Serum‐free medium containing only 1% BSA supports the baseline surface expression of TLR4, and interaction with its natural ligand LPS, and appears to slightly upregulate its expression on the surfaces of adhered prostate cancer (PC3) cells." (PMID 33073533, 2020). "In this review, we have summarized and discussed studies in TLR4 and prostate cancer and emphasized on the pathologic role of TLR4 in prostate cancer oncogenesis." (PMID 29928275, 2018). "In this review, we focus on the pathologic role of TLR4 and its effects in prostate cancer development and progression." (PMID 29928275, 2018). "This provides some insights about TLR4 inhibitors as potential prevention strategies for prostate cancer." (PMID 29928275, 2018). "iNOS has an increased expression in prostate cancer and BPH cells while TLR4 are associated with the alteration of innate immunity and inflammation in prostate cancer." (PMID 28558037, 2017). "There is also evidence of association between prostate cancer risk and gene variants of COX-2, RNASEL and TLR4, identified in cases of hereditary prostate cancer, indicating that infection and the host response to infection may be involved in the development of prostate cancer." (PMID 28101126, 2017). "Activation TLR4 by LPS significantly enhanced survival of prostate cancer cells while TLR4 inhibition by a specific inhibitor led to rapid death of prostate cancer cells." (PMID 27323819, 2016). "In this context, we evaluated functional consequences of TLR2 and TLR4-mediated activation in prostate cancer cells including proliferation, cell attachment, invasion and pro-inflammatory cytokine production." (PMID 24966802, 2014). "The role of TLR4 in the pathophysiology of several age-related diseases is also well recognized, such as prostate cancer (PCa)." (PMID 25360682, 2014). "Although the expression profile of multiple TLRs in cancer cells from different histologically origin has been investigated, few data are available on functional expression of TLR2 and TLR4 in prostate cancer cells." (PMID 24966802, 2014). "Based on the results of Western blot and flow cytometric analyses, we were then about to localize TLR2 and TLR4 expression in prostate cancer cells." (PMID 24966802, 2014). "We here report our findings concerning the role of S100A9 and TLR4 expression using the spontaneous prostate cancer model TRAMP, as well as the transplanted, syngeneic EL4 lymphoma model." (PMID 22470535, 2012). "Conversely, another study reports a decrease in TLR4 expression in human prostate tissue samples that correlates with histopathological grade of prostate cancer." (PMID 22110526, 2011). "Additionally, TLR4 activation by LPS has been shown to promote chemoresistance to docetaxel in prostate cancer cells." (PMID 41601666, 2026). "Dysbiosis in the gut microbiota had been shown to promote the progression of prostate cancer in antibiotic exposure mice via the Toll-like receptor 4 (TLR4) activated transcription factor-κB (NF-κB)—interleukin (IL)−6- signal transducer and activator of transcription 3 (STAT3) axis." (PMID 40576719, 2025). "LPS induced SphK1 S225 phosphorylation in a Toll-like receptor 4 (TLR4)-dependent manner, causing the translocation of SphK1 to plasma membrane, leading to S1P production and ERK1/2 activation, which were required for prostate cancer cell invasion and metastasis." (PMID 37604912, 2023). "However, there have been numerous reports in the literature suggesting a TLR4 role in carcinomas, including pancreatic, colorectal, lung, breast, ovarian and prostate cancer." (PMID 33554122, 2021). "Animal-SELEX was employed recently to identify bone targeting aptamer in a mouse model with prostate cancer bone metastasis, Toll-like receptor 4 (TLR4) blocking aptamers for use as acute stroke treatment, aptamers with the potential to be used as biomarkers for neurological disorders." (PMID 30866536, 2019).